ENSG00000284976 (novel RING finger protein)
Synonyms: LOC122513141
Gene: Protein-coding gene on chromosome 9 (137,217,494 to 137,219,361, forward strand). Ensembl gene ENSG00000284976.
Gene Ontology:
Molecular function: ubiquitin protein ligase activity
Biological process: intrinsic apoptotic signaling pathway in response to endoplasmic reticulum stress; proteasome-mediated ubiquitin-dependent protein catabolic process; protein autoubiquitination; protein K29-linked ubiquitination; protein K63-linked ubiquitination; protein localization to mitochondrion
Cellular component: endoplasmic reticulum membrane